ENSG00000276015
Gene: Miscellaneous RNA gene on chromosome 11 (2,697,851 to 2,698,076, forward strand). Ensembl gene ENSG00000276015.
Gene Ontology:
Biological process: heterochromatin formation
Cellular component: nucleolus